H19 (H19 imprinted maternally expressed transcript)
Diseases named in the same sentence as H19 in open-access papers (continued):
Sharing a sentence is not in itself a finding about the gene and the disease.
breast cancer (continued). "In addition, lncRNA-ATB, metastasis-associated lung adenocarcinoma transcript 1 (MALAT1) and lncRNA H19, which are abnormally expressed in TNBC, may provide a less invasive diagnostic procedure to reveal immunological insight of breast cancer." (PMID 36685907, 2022). "For example, the H19/let 7/Lin28 ceRNA network is involved in autophagy and EMT in breast cancer (BC)." (PMID 35846147, 2022). "Such H19/let-7/Lin28 loop inhibits autophagy and promotes EMT in breast cancer cells by exhibiting a significant positive relationship between H19 (p = 0.0317) and Lin28 (p = 0.0128) expression." (PMID 34885213, 2021). "Recently, lncRNA H19 and LINC01116 have been shown to regulate ERα expression in ERα+ breast cancer cells by functioning as competing endogenous RNA48,49." (PMID 34083547, 2021). "The expression of long non-coding RNA (lncRNA) H19 and LIN28 was correlated with breast cancer’s poor prognosis and metastasis ability." (PMID 35008539, 2021). "Similarly, H19 is responsible for glycolysis and maintenance of breast cancer stem cells thanks to its ability to bind to let-7 miRNA, releasing hypoxia-inducible factor 1α and increasing the expression of pyruvate dehydrogenase kinase 1, protein highly expressed in breast cancer stem cells." (PMID 34439740, 2021). "Similar to H19, lncRNA‐PNUTS serves as a competitive sponge for miR‐205 and miR‐200, leading to the up‐regulation of EMT in breast cancer." (PMID 34977870, 2021). "H19 targets miR-138 to enhance SOX4 expression, leading to enhanced EMT and metastasis in breast cancers and glioma and sponges both miR-138 and miR-194-5-p to promote high mobility group A (HMGA1) expression, EMT and metastasis in CRC." (PMID 32272875, 2020). "High expression of LINC00911, H19, and MIRLRT7BHG, respectively, predicted poor survival in TN breast cancer." (PMID 32190687, 2020). "We first determined the expression of lncRNA H19 and TNFAIP8 in breast cancer tissues and cells by qRT-PCR and western blotting analysis." (PMID 32514245, 2020). "Second, H19 expression is up-regulated in human lung cancers, gastric cancer, CRC, breast cancer, ovary cancer and glioma and associated with poor prognosis in these types of cancers." (PMID 32272875, 2020). "The expression of lncRNA H19 and TNFAIP8 was up-regulated in breast cancer tissues and cell lines, especially in triple-negative breast cancer (TNBC)." (PMID 32514245, 2020). "Taken together, these findings suggest that lncRNA H19 promoted cell growth and EMT process in breast cancer cells, possibly through the positive regulation of TNFAIP8." (PMID 32514245, 2020). "On the contrary, H19 downexpression decreased Dox-induced cell apoptosis and inhibited the Dox response in the Dox-sensitive MCF-7 breast cancer cells." (PMID 32345117, 2020). "H19 downexpression increased Dox-induced cell apoptosis and enhanced the Dox response in the Dox-resistant MCF-7/Dox breast cancer." (PMID 32345117, 2020). "In the current study, we found that lncRNA H19 and TNFAIP8 were markedly enhanced in breast cancer tissues and cell lines, with TNBS cells in particular." (PMID 32514245, 2020).
breast cancer (continued). "A previous study reported that H19 can competitively bind miR-93-5p to upregulate STAT3 and promote proliferation, migration, and invasion in breast cancer." (PMID 33318294, 2020). "Recently, emerging evidence has indicated that lncRNAs play pivotal roles in breast cancer tumourigenesis and progression, such as ANCR, ROR, MEG3 and H19." (PMID 31557401, 2019). "The lncRNA H19 mediates EMT and the reverse process, mesenchymal-to-epithelial transition (MET), in breast cancer, although it has a role as a differential sponge for the microRNAs miR-200b/c and let-7b." (PMID 30619763, 2018). "H19 has been shown to mediate both EMT and MET plasticity by the differential sponging of miR-200b/c and let-7b in breast cancer cells." (PMID 30619763, 2018). "Taken together, these data suggest that CUL4A is a critical component in chemoresistance, and H19, CUL4A, ABCB1 and ABCC4 work coordinately to display the action on modulation of multidrug resistance in breast cancer cells." (PMID 29190892, 2017). "As described in Section 3.2, H19 impairs availability of miR-152 and increases the expression of the epigenetic regulator DNMT1 and so increases proliferation of breast cancer cells lines." (PMID 29099749, 2017). "As let-7 is suppressed by both H19 and LIN28 in breast cancer cells, we analyzed let-7 expression in three paired breast cancer patient samples." (PMID 28102845, 2017). "To address the possibility that the H19/SAHH/DNMT3B pathway mediates metformin effects in other cancer cells, we tested the effects of metformin on the human breast cancer-derived cell line MCF-7." (PMID 27775072, 2017). "Lastly, the expression of HMGA1P7 was significantly correlated with H19 and IGF2 levels in human breast cancer thereby suggesting a role for HMGA1P7 deregulation in this neoplasia." (PMID 27874091, 2016). "A positive correlation was evident between H19 transcription and PTX resistance in the ERα-positive breast cancer cells." (PMID 27845892, 2016). "The contribution of lncRNA H19 to PTX resistance in breast cancer was verified by transfecting the MCF-7R and ZR-75-1R cells with H19-targeting siRNA." (PMID 27845892, 2016). "According to the lncRNADisease Database, there are 16 lncRNAs known to play a role in breast cancer including H19, growth arrest-specific 5 (GAS5), homeobox antisense intergenic RNA (HOTAIR), and breast cancer anti-estrogen resistance 4 (BCAR4)." (PMID 25849966, 2015). "Hormonal regulation of H19 is important, as estradiol is able to stimulate H19 transcription in MCF-7 breast cancer cells, while tamoxifen inhibits this transcription." (PMID 25849966, 2015). "Previously, it was reported that c-MYC, an estrogen-regulated gene in ER+ breast cancer cells, was also able to bind to and activate the transcription of the H19 gene, which indicates that estrogen signaling might in fact indirectly regulate the expression of H19 through the activation of c-MYC." (PMID 25944846, 2015). "Taken together, the present results indicate that the estrogen–ERα–H19 signaling axis plays a role in regulating the proliferation and differentiation potentials of the normal luminal progenitors and that this signaling network may also be important in the development of ER+ breast cancer tumors." (PMID 25944846, 2015). "It would be interesting to investigate if H19 and MIR675 regulate the expression of the GATA3 gene, which is known to play a role in breast cancer development as well as the development and maturation of luminal cells in the mammary gland." (PMID 25944846, 2015).
breast cancer (continued). "Additionally, a growing body of research has identified numerous lincRNAs that facilitate breast cancer metastasis, including lnc-SLC4A1-1, Lnc-BM, BLACAT1, H19, and terminal differentiation-induced ncRNA (TINCR), among others." (PMID 39997609, 2025). "Furthermore, H19 has been shown to regulate the expression of miR-491-5p and inversely modulate ZNF703, playing a critical role in breast cancer development." (PMID 38166752, 2024). "On the other hand, H19 overexpression or reduction did not affect cell proliferation in breast cancer cells, implying that H19-regulated colony formation, spheroid formation, and tumor-initiating activities correlated to self-renewal." (PMID 39170516, 2024). "Furthermore, Spearman correlation heatmap analysis revealed a strong positive correlation among the expressions of LincRNA H19, miR-675, MRP3, HOXA1, and MMP16 in breast cancer tissues." (PMID 39267845, 2024). "In addition to the findings on SNPs and LincRNA H19, this study also investigated the expression of MRP3, HOXA1, and MMP16 in breast cancer tissues." (PMID 39267845, 2024). "In situ hybridization results revealed significant expression differences of LincRNA H19 in breast cancer tissues and adjacent non-tumor tissues." (PMID 39267845, 2024). "Furthermore, lncRNA H19 and lncRNA NEAT1 act upon each other and respectively regulate apoptosis by targeting miR-675 and miR-204 in breast cancer." (PMID 37313458, 2023). "Under hypoxic conditions, the H19/let-7/HIF1 signaling-mediated PDK1 could control glycolysis and further add to breast cancer stem cell maintenance." (PMID 37821504, 2023). "H19 sponges microRNA let-7 to release HIF1-α (Hypoxia-inducible factor 1α), which in turn activates a cascade of target genes, among which the glycolytic enzyme PDK1 (Phosphoinositide-dependent kinase-1) plays a master role in breast cancer stem cells." (PMID 36768150, 2023). "Importantly, they observed that the augmentation of H19 expression hindered the proliferative, migratory, and EMT-suppressive effects mediated by miR-29b-3p in breast cancer cells." (PMID 37705098, 2023). "Hence, lncRNAs, such as DANCR, HOTAIR, H19, and GAS5, are identified as key regulators of autophagy in breast cancer, and further research needs to be carried out to identify their potential in breast cancer diagnosis and treatment." (PMID 36899946, 2023). "Consistently, a higher level of H19 expression was observed in ER+ breast cancer cell lines compared with ER negative breast cancer cell lines." (PMID 37298108, 2023). "Furthermore, it has been demonstrated that by inhibition of H19 and PDK1, aspirin suppresses glycolysis and stemness of breast cancer." (PMID 36429127, 2022). "Through the H19/SAHH/DNMT3B axis, H19 may induce autophagy activation, which may help to produce tamoxifen resistance in breast cancer." (PMID 35813295, 2022). "The downregulation of H19 will significantly reduce colony formation and non-anchored growth of breast cancer and lung cancer cells." (PMID 35882886, 2022). "LncRNA-H19 induces autophagy activation through the H19/SAHH/DNMT3b pathway, which may affect the resistance of breast cancer to tamoxifen." (PMID 36699089, 2022). "H19 functions as a molecular sponge of miR‐152 to upregulate the expression of the DNA methyltransferase DNMT1, thus facilitating the proliferation and invasiveness of breast cancer cells." (PMID 34527584, 2021). "Furthermore, H19 acts as miRNA-130a-3p, sponge leading to upregulation of SATB1, thus promoting breast cancer progression." (PMID 34081618, 2021). "Furthermore, H19 was significantly increased in chemoresistant breast cancer tissues and Doxorubicin-reaiatant MCF-7/Dox cell lines compared with the chemosensitive breast cancer tissues Doxorubicin-sensitive MCF-7 cell lines." (PMID 32345117, 2020).
breast cancer (continued). "The expression of the oncogenic lncRNA H19 has been recognized as a parameter that determines resistance to paclitaxel in ERα-positive breast cancer cells, but not in ERα-negative cells." (PMID 32759784, 2020). "In addition, lncRNA H19 altered the expression of cascades of EMT makers and promoted proliferation, migration and invasion of breast cancer cells through positive regulation of TNFAIP8." (PMID 32514245, 2020). "Moreover, the enhanced expression of lncRNA H19 and TNFAIP8 was also evident in serial breast cancer cell lines, particularly in TNBC cells." (PMID 32514245, 2020). "Although high levels of H19 in breast CSCs (BCSCs) appear to be critically involved in sustaining BCSC properties, there are findings indicating that neither depletion nor overexpression of H19 affect breast cancer proliferation." (PMID 32932969, 2020). "The migratory capacities of breast cancer cells overexpressing or not H19 or miR-675 were determined by using Transwell assays." (PMID 32610610, 2020). "We further investigated whether inhibiting or increasing H19 expression could modulate cell survival and the sensitivity of MCF-7 and MCF-7/Dox cells to Dox, which is currently used for the treatment of breast cancer." (PMID 32345117, 2020). "Moreover, H19 increases the expression of DNMT1, a DNA methyltransferase, by sponging miR-152, thus inducing the growth and invasion of breast cancer cells." (PMID 32610610, 2020). "The suppression in H19 expression by IDET may be another possibility for the inhibition of NF-κB activation and sensitization of breast cancer cells to doxorubicin." (PMID 31784542, 2019). "Our findings demonstrate that H19 induces autophagy activation via the H19/SAHH/DNMT3B axis, which could contribute to tamoxifen resistance in breast cancer." (PMID 31340867, 2019). "To better understand the shared impact of lncRNAs and miRNAs in the regulatory post‐transcriptional network, we focused here on the relationships between (a) lncRNA H19 and miR‐675, (b) NEAT1 and miR‐204, and (c) HOTAIR and miR‐331 in plasma of early breast cancer (BC) patients." (PMID 30803129, 2019). "Interestingly, H19 was also increased in paclitaxel (PTX, often used post-surgery to kill remaining cancer cells) resistant ER+ breast cancer cells." (PMID 29719633, 2018). "To identify further whether PDK1 is the potential downstream targets of H19, we first examined PDK1 expression upon H19 knockdown in breast cancer cells." (PMID 29106390, 2018). "Similar results have found that lncRNA H19 correlates positively with LIN28 by acting as a ceRNA for miRNA let-7, to form a double-negative feedback loop, thereby regulating the maintenance of breast cancer CSCs." (PMID 30482236, 2018). "Accordingly, H19 and PDK1 expression exhibits strong correlations in primary breast carcinomas." (PMID 29106390, 2018). "Using genetic and pharmacological approaches, we demonstrated that MDR1 and MRP4 were major effectors of H19-regulated Dox resistance in breast cancer cells as MDR1 and MRP4 expression was markedly elevated in Dox-resistant cells while dramatically reduced when H19 was knocked down." (PMID 29190892, 2017). "In breast cancer, the expression of H19 is higher in Estrogen receptor (ERα) positive cells, but in the ERα negative MDA-MB-231 cell line, ectopic overexpression of H19 is associated with increased proliferation." (PMID 29099749, 2017). "Interestingly, another lncRNA from the same gene locus named 91H, which is the antisense of H19, also regulates IGF2 expression in esophageal squamous cell carcinoma and breast cancer." (PMID 28230721, 2017). "Thus, we identify a novel negative-feedback mechanism between H19 and let-7, as well as a double-positive feedback loop between H19 and LIN28 mediated through let-7 in breast cancer." (PMID 28102845, 2017).
breast cancer (continued). "It was observed that knockdown of H19 significantly reversed resistance even to drugs that were not substrates of P-glycoprotein, indicating H19 induced breast cancer chemoresistance through multiple mechanisms." (PMID 29299178, 2017). "Appropriately, H19 and LIN28 expression exhibits strong correlations in primary breast carcinomas." (PMID 28102845, 2017). "Moreover, H19 has the potential to produce 91H RNA, which regulates insulin like growth factor 2 (IGF2) expression and is over-expressed in breast cancer cells." (PMID 27027436, 2016). "Lu's breast cancer dataset with 129 samples showed a higher expression of H19 in ERα-positive (n = 76) than ERα-negative (n = 53) breast cancers, which suggested a possible involvement of ERα in the upregulation of H19 in chemoresistant cancer cells." (PMID 27845892, 2016). "We propose that the ERα-H19-BIK axis may be a novel therapeutic target for treatment of patients with ERα-positive, chemoresistant breast cancer." (PMID 27845892, 2016). "Then, we investigated whether HMGA1P7 functions as ceRNA through, or partially through H19, IGF2 and HMGA1 in breast cancer human cells." (PMID 27874091, 2016). "In addition, hypoxia induces H19 and miR-675 as well as the EMT markers Slug and Snail in breast cancer cells." (PMID 26536864, 2015). "For instance, H19, which is overexpressed in the basal-like breast cancer subgroup, was enriched for genes with HCP marked by H3K4me2 and H3K4me3, suggesting that H19 may interact with the trithorax group of proteins, which maintains gene expression." (PMID 25296969, 2014). "A correlation between H19 and E2F1 expression levels in breast cancer was also revealed." (PMID 23429271, 2013). "In particular, hypoxia can increase the expression of lncRNA H19, which functions as a ceRNA to bind miRNA let-7 with EZH2 mRNA in a competitive manner, so indirectly increasing EZH2 expression and encouraging the invasion and metastasis of breast cancer cells." (PMID 41614928, 2026). "Interestingly, H19 expression was also elevated in 3D cultures of MDA-MB-231, particularly in the breast cancer stem cell population, suggesting that this interaction might be present and enhanced in 3D cultures of BT-474 cells." (PMID 41163216, 2025). "Consequently, the ultimate aim of our study is to investigate a possible relationship between H19, hTERT, and glycolytic metabolism that could be modulated by ATRA in breast cancer." (PMID 38773429, 2024). "Furthermore, the AG genotype at rs11042167 and the GT genotype at rs2071095 were positively correlated with the expression of LincRNA H19 and miR-675 (P < 0.001), supporting the potential of the H19/LincRNA H19/miR-675/MRP3-HOXA1-MMP16 axis as a new direction for targeted therapy in breast cancer." (PMID 39267845, 2024). "However, there are additional emerging lncRNAs that have been described as potential biomarkers in cancer, such as HOTAIR, DSCAM-AS1, and GATA3-AS1 in breast cancer, MALAT1 in lung cancer, H19 in colorectal cancer, HULC in liver cancer, UCA1 in bladder cancer, and DLEU1 in endometrial cancer." (PMID 37108589, 2023). "In detail, H19 serves as the precursor of miR-675 and promotes it to directly target c-Cbl and Cbl-b mRNA so as to decrease their expression, leading to sustained activation of AKT and ERK pathways as well as enhanced cell proliferation and migration in breast cancers both in vitro and in vivo." (PMID 36246634, 2022). "Additionally, Let-7 can be regulated by LncRNA H19 and LIN28 in breast cancer." (PMID 35008539, 2021). "LncRNA H19 acts as a ceRNA to the sponge let-7, which upregulates Lin28 expression and may form a double-negative feedback loop in the maintenance of breast cancer stem cells." (PMID 32575858, 2020). "However, the biological mechanism of H19 in regulating doxorubicin sensitivity in breast cancer has not been fully elucidated." (PMID 32345117, 2020).